APOC3 (apolipoprotein C3)
Description:
Component of triglyceride-rich very low density lipoproteins (VLDL) and high density lipoproteins (HDL) in plasma. Plays a multifaceted role in triglyceride homeostasis. Intracellularly, promotes hepatic very low density lipoprotein 1 (VLDL1) assembly and secretion; extracellularly, attenuates hydrolysis and clearance of triglyceride-rich lipoproteins (TRLs). Impairs the lipolysis of TRLs by inhibiting lipoprotein lipase and the hepatic uptake of TRLs by remnant receptors. Formed of several curved helices connected via semiflexible hinges, so that it can wrap tightly around the curved micelle surface and easily adapt to the different diameters of its natural binding partners.
Synonyms: Apo-CIII; ApoC-III; APOCIII; Apo-C3; ApoC-3
Tractability: Antibody: its Gene Ontology location is reachable by antibodies, with high confidence; UniProt places it where antibodies can reach, with medium confidence; UniProt predicts a signal peptide or a membrane-spanning region. PROTAC: ubiquitination databases record sites on it.
Safety:
Unwanted effects reported when the protein is acted on. In parentheses: how it was acted on, where the effect was seen, and who reports it.
triglyceride elevation (source: ClinPGx)
triglyceride levels (source: ClinPGx)
Gene: Protein-coding gene on chromosome 11 (116,827,019 to 116,833,343, forward strand). Ensembl gene ENSG00000110245.
Subcellular location: Secreted
Subcellular location (Human Protein Atlas): Nucleoplasm; Cell Junctions; Nucleoli; Predicted to be secreted
Pathways (Reactome):
Transport of small molecules: Chylomicron assembly; Chylomicron remodeling; HDL remodeling
Sensory Perception: Retinoid metabolism and transport
Gene Ontology:
Molecular function: high-density lipoprotein particle receptor binding; lipase inhibitor activity; phospholipid binding; protein binding; cholesterol binding; lipid binding
Biological process: cholesterol efflux; cholesterol homeostasis; chylomicron remnant clearance; G protein-coupled receptor signaling pathway; high-density lipoprotein particle remodeling; lipid transport; negative regulation of cholesterol import; negative regulation of fatty acid biosynthetic process; negative regulation of high-density lipoprotein particle clearance; negative regulation of lipid catabolic process; negative regulation of lipid metabolic process; negative regulation of low-density lipoprotein particle clearance; negative regulation of receptor-mediated endocytosis; negative regulation of triglyceride catabolic process; negative regulation of very-low-density lipoprotein particle clearance; negative regulation of very-low-density lipoprotein particle remodeling; phospholipid efflux; regulation of Cdc42 protein signal transduction; triglyceride catabolic process; triglyceride homeostasis; triglyceride metabolic process; reverse cholesterol transport; very-low-density lipoprotein particle assembly; lipoprotein metabolic process
Cellular component: chylomicron; extracellular exosome; extracellular region; intermediate-density lipoprotein particle; spherical high-density lipoprotein particle; very-low-density lipoprotein particle; early endosome
Genetic constraint (gnomAD): Loss-of-function variants: 8 observed, 8.26 expected, observed/expected ratio (o/e) 0.97, 90% interval 0.56 to 1.68. That is too few expected variants to judge how well the gene tolerates losing a copy. Missense variants: 123 observed, 130.57 expected, observed/expected ratio (o/e) 0.94, 90% interval 0.81 to 1.09. Synonymous variants: 45 observed, 53.56 expected, observed/expected ratio (o/e) 0.84, 90% interval 0.66 to 1.08.
Homologues: Orthologues: chimpanzee APOC3 (97% identical), dog APOC3 (75% identical), pig APOC3 (66% identical), mouse Apoc3 (62% identical), guinea pig Apoc3 (48% identical), rat Apoc3 (44% identical).
Diseases named in the same sentence as APOC3 in open-access papers:
APOC3 is named in the same sentence as 217 diseases in open-access papers, as found by Europe PMC text mining. Sharing a sentence is not in itself a finding about the gene and the disease. The quoted sentences say what the papers report.
hypertriglyceridemia (193 papers, 2006 to 2026). A laboratory test result indicating elevated triglyceride concentration in the blood. "Cyp7b1-deficient rats are resistant to postprandial hypertriglyceridemia, a common feature with mice expressing human lipoprotein lipase and Apoc3-deficient mice." (PMID 41465421, 2025). "The development of olezarsen was directly informed by these insights, effectively translating the protective effect of APOC3 deficiency into a therapeutic strategy for the treatment of hypertriglyceridemia." (PMID 41393714, 2025). "In contrast, polygenic hypertriglyceridemia and carriers of APOC3 or APOB variants exhibited a markedly higher prevalence of MASLD (65–70%)." (PMID 41300829, 2025). "Elevated ApoC3 levels have previously been associated with hypertriglyceridemia, increased CVD risk, and pancreatitis risk." (PMID 40264627, 2025). "ApoC3 has therefore become an increasingly attractive target for reducing cardiovascular risk in patients with hypertriglyceridemia, with several antisense oligonucleotide therapies and hepatocyte‐targeted siRNAs being developed against ApoC3." (PMID 40981413, 2025). "Transgenic mice expressing ApoC3 exhibit persistent hypertriglyceridemia from birth, while ApoC3 deficiency in mice leads to enhanced TG hydrolysis and clearance, resulting in reduced circulating TG levels." (PMID 38441531, 2024). "Elevated APOC3 levels contribute to increased insulin resistance, leading to a cycle that worsens hypertriglyceridemia and raises the risk of metabolic syndrome and type 2 diabetes." (PMID 39286687, 2024). "Plasma APOC3 is positively associated with triglyceride levels, and APOC3 is therefore often elevated in states associated with hypertriglyceridemia and insulin resistance." (PMID 37972731, 2024). "Lowering APOC3 levels has been shown to reduce TG levels in humans and animal models, and elevated APOC3 levels are strongly correlated with hypertriglyceridemia and an increased CVD risk." (PMID 39684468, 2024). "Diets high in saturated fats, refined carbohydrates, and sugars have been shown to elevate the APOC3 levels, contributing to hypertriglyceridemia and promoting lipid abnormalities associated with atherosclerosis." (PMID 39684468, 2024). "Several research studies have emphasized the role of APOC3 in the development and progression of severe hypertriglyceridemia, providing valuable insights into the underlying mechanisms and possible treatment targets." (PMID 39286687, 2024). "This method emphasizes the potential of therapies focused on lowering APOC3 to target the cause of severe hypertriglyceridemia." (PMID 39286687, 2024). "Elevated plasma levels of APOC3 are also considered as a major risk factor for hypertriglyceridemia." (PMID 35237305, 2022). "Apoprotein C3 (APOC3) is a key regulator of the metabolism of lipoprotein and has been demonstrated to be closely associated with hypertriglyceridemia." (PMID 35449866, 2022). "High levels of apolipoprotein C3 (APOC3) can lead to hypertriglyceridemia, which increases the risk of cardiovascular disease." (PMID 34922545, 2021). "In contrast, overexpression of human APOC3 in transgenic mice is associated with hypertriglyceridemia." (PMID 31111320, 2019). "Since inhibition of apoC3 expression is currently being considered as a treatment of hypertriglyceridemia, one must keep in mind the potential risk of NAFLD and NASH." (PMID 30355853, 2018). "Apolipoprotein C3 (APOC3) is a major regulator of plasma triglyceride levels, and its overexpression is closely associated with hypertriglyceridaemia in patients with metabolic syndrome." (PMID 29419487, 2018). "A high level of ApoC3 correlates with hypertriglyceridemia and is often associated with coronary heart disease and atherosclerosis." (PMID 28210565, 2017). "Additional copies of human APOC3 in transgenic pig were associated with hypertriglyceridemia (HTG), whereas APOC3 deficiency prevents hyperlipidemia induced by apolipoprotein E gene overexpression." (PMID 25928461, 2015).
hypertriglyceridemia (continued). "Genetic biomarkers on the APOC3 (C-482T and T-455C) gene have been associated with hypertriglyceridemia in several distinct populations and their presence reduces APOC3 protein expression." (PMID 24972136, 2014). "Carriers of non-E3/E3 genotypes of APOE appear to be at risk of ritonavir-associated hypertriglyceridemia, and this risk appears to be enhanced by the association with APOC3 variants." (PMID 24191141, 2013). "According to the SHCS, the interaction between APOE and APOC3 is associated with an extreme risk of developing hypertriglyceridemia in individuals treated with ritonavir." (PMID 24191141, 2013). "Conversely, two sequence variants in apolipoprotein C3 (APOC3) that have been linked to hypertriglyceridemia (rs2854117 C > T and rs2854116 T > C) have recently been reported to be associated with both hepatic fat content and insulin resistance." (PMID 21274868, 2011). "Experimental studies have demonstrated that overexpression of APOC3 causes delayed clearance of TG-rich lipoproteins from plasma, resulting in hypertriglyceridaemia." (PMID 21663607, 2011). "APOC3 was the first lipid-associated gene to be linked by a common polymorphism to hypertriglyceridemia." (PMID 22054125, 2011). "Several polymorphisms in the apolipoprotein C3 (APOC3) gene have been found association with hypertriglyceridemia(HTG), but the link with coronary heart disease(CHD) risk between ethnicities was still controversial." (PMID 22054125, 2011). "Lastly, the prevalence of hypertriglyceridemia was higher in carriers of the APOA5 Trp19 allele (35%) than in carriers of the APOC3 -482T (23%) or APOC3 3238G (22%) alleles and thus increased the probability of fulfilling the definition of metabolic syndrome." (PMID 18789138, 2008). "This protective effect is consistent with APOC3 inhibition via volanesorsen reducing hepatic steatosis in patients with hypertriglyceridemia, and substantial evidence suggests APOC3 deficiency, unlike APOB deficiency, is cardioprotective without causing steatosis." (PMID 40065360, 2025). "Not long ago, ApoC3 polymorphisms were associated with the lean male population’s susceptibility to NAFLD and insulin resistance leading to a rise in ApoC3 plasma levels by approximately 30% and postprandial hypertriglyceridemia caused by ApoC3’s altering effect on lipoprotein lipase activity." (PMID 38921259, 2024). "However, the association between APOC3-induced hypertriglyceridemia and islet β-cells remains to be elucidated." (PMID 39684468, 2024). "Our MR study suggests that the genetically regulated hypertriglyceridemia via APOC3 may be causally associated with the increased risk for CAD." (PMID 34548093, 2021). "As well, a gain-of-function mutation in APOC3 was revealed as a new cause for hypertriglyceridemia." (PMID 32041611, 2020). "Because human studies convincingly show that loss-of-function mutations in APOC3 are associated with lower TG levels and cardioprotection, APOC3 has recently emerged as a drug target for the treatment of hypertriglyceridemia and possibly the associated increase in CVD risk." (PMID 32849290, 2020). "APOC3 is associated with hypertriglyceridemia and elevates plasma triglyceride levels by preventing clearance of very-low-density lipoproteins (VLDLs) and high-density lipoproteins (HDLs) but limited research is available denoting its presence or role in placental function." (PMID 32998709, 2020). "APOC3 is known to encode protein apolipoprotein C-III, which is highly associated with hypertriglyceridemia and its altered metabolism may lead to dyslipidemia in chronic kidney disease (CKD)." (PMID 32392242, 2020). "A prospective case–control study suggested that APOC3 (−455 T > C) genetic variation was involved in the susceptibility to developing nonalcoholic fatty liver disease, insulin resistance, hypertension, hypertriglyceridemia, and low HDL in the Southern Chinese Han population." (PMID 25994187, 2015).
hypertriglyceridemia (continued). "Common polymorphisms in the promoter of the APOC3 gene have been associated with hypertriglyceridemia and may impact on phenotypic expression of the metabolic syndrome (MetS)." (PMID 18096054, 2007). "Therefore, it may be hypothesized that the variants of APOA1 and APOC3 might confer to hypertriglyceridemia, thereby leading to characteristic feature of atherogenic dyslipidemia among this south Indian population." (PMID 28610615, 2017). "Exploring the role of APOC3 in managing lipid levels and its impact on hypertriglyceridemia offers new possibilities for treatment options." (PMID 39286687, 2024). "Hepatic FoxO1, associated with insulin resistance, plays a crucial role in impairing ApoC3 production and contributing to hypertriglyceridemia in obese mice." (PMID 38441531, 2024). "While ApoC3’s pivotal role in the pathogenesis of hypertriglyceridemia is well-established, its precise biological function in NAFLD remains elusive." (PMID 38441531, 2024). "Recent genetic studies and clinical trials have shed light on the potential of targeting APOC3 as a potentially promising therapeutic modality of hypertriglyceridemia." (PMID 39286687, 2024). "By examining research on APOC3, the goal was to uncover how this gene influences triglyceride levels and investigate potential treatment implications by targeting APOC3 for severe hypertriglyceridemia management." (PMID 39286687, 2024). "By deepening our knowledge of APOC3 and harnessing state-of-the-art methods, we can make strides toward personalized treatments for severe hypertriglyceridemia, ultimately improving the quality of life for individuals affected by this disorder." (PMID 39286687, 2024). "This collective evidence highlights the connection both ApoC3 and hypertriglyceridemia, positioning ApoC3 as a potential therapeutic mark for managing elevated TG levels." (PMID 38441531, 2024). "Genetic research highlights the role of APOC3 in triglyceride metabolism, while clinical trials demonstrate the potential benefits of targeting APOC3 for treating severe hypertriglyceridemia." (PMID 39286687, 2024). "Addressing hypertriglyceridemia typically involves making lifestyle changes using medications as well as considering available and upcoming therapies that target APOC3." (PMID 39286687, 2024). "Studying APOC3 and severe hypertriglyceridemia provides insights with significant treatment implications." (PMID 39286687, 2024). "This review article delves into how APOC3 influences triglyceride control and its potential use in targeting APOC3 to manage severe hypertriglyceridemia." (PMID 39286687, 2024). "Studying diverse populations can lead to the discovery of new mutations and their effects, offering fresh perspectives on the involvement of APOC3 in conditions like hypertriglyceridemia and other lipid disorders." (PMID 39286687, 2024). "New treatments focusing on APOC3 show promise as an approach to managing severe hypertriglyceridemia." (PMID 39286687, 2024). "Apolipoprotein C-III (APOC3), a protein for lipid metabolism, hinders enzymes necessary for breaking down triglycerides and thus plays a key role in hypertriglyceridemia." (PMID 39286687, 2024). "This review of the existing literature aimed to offer insight into how APOC3 impacts adults with hypertriglyceridemia." (PMID 39286687, 2024). "The advancement of therapies targeting APOC3 shows potential for enhancing the management of severe hypertriglyceridemia." (PMID 39286687, 2024). "This particular protein raises apolipoprotein C3 levels, which subsequently favorizes the storage of very-low-density lipoprotein (VLDL) over lipids into cells, causing hypertriglyceridemia." (PMID 38921259, 2024). "Volanesorsen (Ionis Pharmaceuticals) is an antisense oligonucleotide that inhibits hepatic synthesis of ApoC3 and used for the treatment of familial chylomicronemia syndrome, familial partial lipodystrophy, and hypertriglyceridemia." (PMID 36691918, 2023).
hypertriglyceridemia (continued). "The ApoA1 and ApoA4 genes have the same transcriptional direction, while ApoC3 is transcribed in the opposite direction; moreover, its polymorphic variation can lead to hypertriglyceridemia." (PMID 32795354, 2020). "This polymorphism leads to a roughly 30% higher plasma concentration of ApoC3, and postprandial hypertriglyceridaemia." (PMID 34394242, 2020). "Transgenic expression of Apoc3 results in hypertriglyceridemia in mice, whereas gene targeted deletion of Apoc3 decreases TG levels." (PMID 31092690, 2019). "The increase in the level of APOC3 results in hypertriglyceridemia which is a metabolic complication of the retinoid therapy." (PMID 31207142, 2019). "Apolipoprotein C3 (APOC3) is an important regulator of lipoprotein metabolism, and has been shown to be strongly associated with hypertriglyceridemia." (PMID 30380775, 2018). "For example, the T3206G polymorphism of the APOC3 gene is closely related to the blood lipids in hypertriglyceridemia, and the serum level of TG in ApoC3 G3175G genotype carriers is higher than those of other genotypes." (PMID 29132372, 2017). "The values of the area under the ROC curve (AUC) for predicting hypertriglyceridemia were most significant by sdLDL-C (0.845, 95% CI 0.809-0.881, p < 0.001), followed by apoC3 (0.805, 95% CI 0.767-0.843, p < 0.001)." (PMID 27713142, 2017). "As a result, the level of circulating APOC3 increases and acts as alipoprotein lipase inhibitor, leading to decreased clearance of TG-rich particles, which ultimately result in hypertriglyceridemia." (PMID 26965314, 2016). "ApoC3 kinetics was measured in an in vivo study, which suggested that all ApoC3 isoforms, especially the predominant C31 and C32 isoforms, contribute to hypertriglyceridemia." (PMID 26090384, 2015). "Studies have shown that excess apoC3 results in hypertriglyceridemia due to delayed catabolism of VLDL and chylomicron remnants, and thus we examined the levels of apoC3 associated with the d < 1.019 g/ml fraction by immunoblot analysis." (PMID 26061292, 2015). "Animal and human studies have shown a strong positive correlation between plasma apoC3 and triglyceride concentrations, and ApoC3 transgenic mice show severe hypertriglyceridemia." (PMID 25302499, 2014). "The suggested mechanism involves therefore increased plasma concentrations of apolipoprotein C3, which in turn inhibits lipoprotein lipase and triglyceride clearance, and consequently increases fasting and post-prandial hypertriglyceridaemia." (PMID 21663607, 2011). "Notably, Imamura described two cases of psoriasis patients with hypertriglyceridemia and demonstrated a reduction in ApoC3 and ApoE levels following clofibrate treatment." (PMID 40137160, 2025). "Apolipoprotein C-III (APOC3) inhibitors are approved for hypertriglyceridaemia." (PMID 40161303, 2025). "Additionally, transgenic and knockout mouse models have reinforced these findings, demonstrating that APOC3 overexpression induces hypertriglyceridemia, whereas its absence promotes efficient lipid clearance and a favourable cardiovascular profile." (PMID 40282372, 2025). "Apolipoprotein C3 (ApoC3) was initially recognized for its role in promoting hypertriglyceridemia." (PMID 40981413, 2025). "The discovery of a non-coding isoform (Novel-3) suggests that promoting exon 2 skipping could serve as a strategy to lower functional APOC3 levels, with potential benefits for hypertriglyceridemia treatment." (PMID 40282372, 2025). "These advancements suggest that APOC3-targeted therapies could offer more management options for hypertriglyceridemia than traditional methods." (PMID 39286687, 2024). "The impact of APOC3 on hypertriglyceridemia has been extensively studied." (PMID 39286687, 2024). "This has spurred the development of treatments targeting APOC3 to manage hypertriglyceridemia." (PMID 39286687, 2024). "In summary, the link between APOC3 and severe hypertriglyceridemia is intricate and diverse." (PMID 39286687, 2024).